PIERCE1 (piercer of microtubule wall 1)
Description:
Microtubule inner protein involved in the attachment of outer dynein arms (ODAs) to dynein-decorated doublet microtubules (DMTs) in cilia axoneme, which is required for motile cilia beating. Functions at the initial step of left-right asymmetry specification of the visceral organs.
Synonyms: MGC29761; RbEST47; C9orf116
Tractability: Small molecule: a structure with a bound ligand is known. PROTAC: ubiquitination databases record sites on it.
Gene: Protein-coding gene on chromosome 9 (135,495,180 to 135,501,734, reverse strand). Ensembl gene ENSG00000160345.
Subcellular location: Cytoplasm, cytoskeleton, cilium axoneme; Cytoplasm, cytoskeleton, flagellum axoneme
Subcellular location (Human Protein Atlas): Mid piece; Nucleoplasm; Cytosol
Gene Ontology:
Molecular function: protein binding
Biological process: axoneme assembly; cilium movement; determination of left/right symmetry; establishment of left/right asymmetry; flagellated sperm motility
Cellular component: axonemal microtubule; axonemal A tubule inner sheath; cytoplasm; nucleus; sperm flagellum; axoneme
Genetic constraint (gnomAD): Loss-of-function variants: 12 observed, 11.37 expected, observed/expected ratio (o/e) 1.06, 90% interval 0.67 to 1.67. The upper end of that interval is the gene's LOEUF score, 1.67, which puts it in group 6 of 6, group 1 being the genes least tolerant of losing a copy. Missense variants: 176 observed, 189.55 expected, observed/expected ratio (o/e) 0.93, 90% interval 0.82 to 1.05. Synonymous variants: 89 observed, 78.42 expected, observed/expected ratio (o/e) 1.13, 90% interval 0.95 to 1.35.
Homologues: Orthologues: chimpanzee PIERCE1 (100% identical), macaque PIERCE1 (96% identical), pig PIERCE1 (81% identical), guinea pig PIERCE1 (76% identical), mouse Pierce1 (74% identical), rat Pierce1 (71% identical), tropical clawed frog c8h9orf116 (46% identical), zebrafish pierce1 (38% identical), Drosophila melanogaster CG34107 (26% identical). Paralogues in human: PIERCE2 (23% identical).
Diseases named in the same sentence as PIERCE1 in open-access papers:
PIERCE1 is named in the same sentence as 10 diseases in open-access papers, as found by Europe PMC text mining. Sharing a sentence is not in itself a finding about the gene and the disease. The quoted sentences say what the papers report.
Situs inversus totalis (2 papers, 2016 to 2020). "In this study, we found that Pierce1-null mice exhibit severe laterality defects, including situs inversus totalis and heterotaxy with randomized situs and left and right isomerisms." (PMID 27305836, 2016). "In vivo analyses of PIERCE1 knockout (KO) mice revealed that approximately half of PIERCE1 homozygous KO mice exhibit embryonic lethality due to developmental defects, and 40% of survivors have situs inversus totalis, which reverses all organs from their normal positions." (PMID 32745107, 2020).
ciliopathies (1 paper, 2021). "Our functional characterization demonstrates that the Pierce1 and Pierce2 genes are important for ciliary motility and that their genetic loss causes ciliopathy-like phenotypes." (PMID 34715025, 2021). "The structural information also provides a framework to interrogate the roles of individual axonemal proteins and their contribution to ciliary motility and ciliopathies, as we demonstrate for Pierce1 and Pierce2." (PMID 34715025, 2021).
lung adenocarcinoma (1 paper, 2020). A carcinoma that arises from the lung and is characterized by the presence of malignant glandular epithelial cells. "Intriguingly, the increased PIERCE1 expression in lung adenocarcinoma was found to have significant (P < 0.05) correlations with KRAS mutation status." (PMID 32728173, 2020). "Here, we explored the underlying mechanisms of action of PIERCE1 in KRAS-mutant lung cancer, which accounts for 30% of all lung adenocarcinoma cases." (PMID 32728173, 2020). "Gene expression profiles previously reported for two different NSCLC cohorts revealed increased PIERCE1 expression in lung adenocarcinomas compared to large- and squamous-cell carcinomas." (PMID 32728173, 2020). "This suggests a tumor-promoting function of PIERCE1 in KRAS-mutant lung adenocarcinomas." (PMID 32728173, 2020). "Moreover, ablation of RB, one of the major suppressors of PIERCE1 expression, accelerates tumor progression in lung adenocarcinoma, potentiating our hypothesis." (PMID 32728173, 2020).
lung carcinoma (1 paper, 2020). "Similarly, in vivo analyses of PIERCE1 depletion in the KRAS mutation-related lung cancer mouse models revealed the suppressive effect of PIERCE1 knockout in urethane- and KRASG12D-induced lung tumorigenesis with decreased pAKT levels observed in the tumors." (PMID 32728173, 2020). "The middle and high PIERCE1 expression groups were counted as PIERCE1-positive lung cancer samples which account for 83.4% of the cases, suggesting that PIERCE1 is expressed in most lung cancer patients." (PMID 32728173, 2020). "The cancer promoting activity and lung-specific expression of PIERCE1 prompted us to examine the link between PIERCE1 and lung cancer." (PMID 32728173, 2020). "Collectively, these data suggest that PIERCE1 inhibition provides clinical benefit particularly for mutant KRAS-driven lung cancer." (PMID 32728173, 2020). "For this investigation, PIERCE1 KO mice were crossed with KRASLA2 mice to generate mutant KRAS-induced spontaneous lung cancers." (PMID 32728173, 2020). "Tissue microarrays of human lung cancers indicated the expression of PIERCE1 in 83% of lung cancers and its correlation with pAKT expression." (PMID 32728173, 2020). "To confirm this, we generated PIERCE1 stable KD cell lines constitutively expressing the shRNA targeting PIERCE1 transcript using two additional lung cancer cell lines, A549 and H460." (PMID 32728173, 2020). "Expressional analyses in tissue microarray of human lung cancer specimens were performed to investigate PIERCE1 and pAKT levels." (PMID 32728173, 2020). "Transient KD of PIERCE1 expression hindered proliferation of five of seven lung cancer cell lines (H358, H1373, H3122, H226, and HCC827); however, no changes were detected in PC-9 and H1299 cell lines." (PMID 32728173, 2020). "Intervention of PIERCE and AKT in ER stress-induced TRIB3 expression shows that PIERCE1 modulates AKT phosphorylation in mutant KRAS-driven lung cancer." (PMID 32728173, 2020). "Taken together, these data suggest that PIERCE1 is involved in the proliferation of KRAS-mutant lung cancer cells." (PMID 32728173, 2020). "To identify the types of lung cancer cells where PIERCE1 plays a role as a tumor-promoting factor, we examined PIERCE1 expression patterns according to cellular traits and genetic mutation status." (PMID 32728173, 2020). "Although KD efficiency should be improved as only a 50% decrease in PIERCE1 expression was observed, siRNA-mediated PIERCE1 KD suppressed tumor growth in KRAS-mutant lung cancer." (PMID 32728173, 2020). "AKT plays important roles in mutant KRAS-driven cancers and the increased expression pattern of PIERCE1 has been detected in patients with KRAS-mutant type lung cancers." (PMID 32728173, 2020). "Based on PIERCE1 expression levels in normal and lung cancer tissues, NSCLC samples were split into three groups, namely, low PIERCE1 expression (expression levels similar to those of normal lung tissues), middle (expression degree 10–40%), and high (expression degree higher than 40%)." (PMID 32728173, 2020). "Tumor allograft studies also suggest the potential of an anti-PIERCE1 lung cancer therapy." (PMID 32728173, 2020). "Correspondingly, doxycycline-induced PIERCE1 overexpression promoted cell proliferation in A549 cells compared to controls, suggesting that PIERCE1 is required for the proliferation of most lung cancer cell lines." (PMID 32728173, 2020). "PIERCE1 depletion successfully suppressed tumor cell growth and decreased AKT phosphorylation, specifically in KRAS-mutant lung cancer cells." (PMID 32728173, 2020). "Importantly, of those middle and high PIERCE1 expression specimens, 75% of tumor samples showed co-expression patterns with pAKT, with only two exceptional cases, thereby suggesting that PIERCE1 expression is linked to the activation of the AKT pathway in human lung cancer." (PMID 32728173, 2020).
lung carcinoma (continued). "Mechanistically, PIERCE1 depletion inhibits cell growth and AKT phosphorylation (pAKT) at S473, which is particularly observed in KRAS-mutant lung cancers." (PMID 32728173, 2020). "Notably, growths of all KRAS-mutant cells (A549, H358, H460, and H1373) were attenuated by PIERCE1 KD, while half of KRAS WT lung cancer cell lines (H3122, H226, HCC827, PC-9, H1299, and Heas-2B) were responsive to PIERCE1 depletion." (PMID 32728173, 2020). "This study reveals that the antitumorigenic effect of PIERCE1 depletion is controlled by the AKT pathway in lung cancer, while ERK activity is not affected by PIERCE1." (PMID 32728173, 2020). "Furthermore, quantitative analysis of PIERCE1 and TRIB3 expression in lung cancer patients revealed their negative interrelationship, thereby confirming the correlation that PIERCE1 suppresses TRIB3 in human lung cancer patients." (PMID 32728173, 2020).
situs inversus (1 paper, 2020). A congenital condition in which there is complete right-to-left reversal of the position of the major thoracic and abdominal organs (that is, they are arranged in a mirror image of the normal positioning). "Although the complete KO of PIERCE1 does not affect mouse phenotype after birth and no evident differences in AKT phosphorylation were detected in normal tissues, this may be due to the partial embryonic lethality caused by incomplete situs inversus (heterotaxy)." (PMID 32728173, 2020).
cancer (2 papers, 2020). A tumor composed of atypical neoplastic, often pleomorphic cells that invade other tissues. "Moreover, we showed that inhibition of PIERCE1 expression before and after the onset of tumorigenesis effectively hindered cancer cell growth." (PMID 32728173, 2020). "However, unlike mice, the PIERCE1 mRNA level was not changed by cisplatin in human primary fibroblast and cancer cell lines, but the p21 mRNA level increased." (PMID 32745107, 2020).
tumor (2 papers, 2020). "Here, we show the tumor-promoting function of a cell cycle-related protein, PIERCE1, in KRAS-mutant NSCLC." (PMID 32728173, 2020). "Similar to our in vitro results, immunohistochemical analyses of the lungs of KRASLA2 mice showed decreased pAKT and increased TRIB3 expression in tumor mass of PIERCE1 KO mice, implying that ablation of PIERCE1 suppresses lung tumorigenesis with impaired AKT activity in vivo." (PMID 32728173, 2020). "Correspondingly, tumor volume and weight were suppressed by up to 70% by siRNA-mediated PIERCE1 KD." (PMID 32728173, 2020). "Moreover, by injecting these cell lines into the flank regions of nude mice in a tumor xenograft model confirmed that PIERCE1 KD-induced growth impairment could be rescued by AKT overexpression." (PMID 32728173, 2020). "In addition, the tumor suppressive function of PIERCE1 is not tightly limited to mutant KRAS expression because it also hinders cell growth in WT KRAS expressing cells." (PMID 32728173, 2020).
PIERCE1 also shares sentences with these, for which no sentence is quoted: lung squamous-cell carcinomas (1 paper); non-small cell lung carcinoma (1); squamous cell carcinoma (1).